NQO1 (NAD(P)H quinone dehydrogenase 1)
Diseases named in the same sentence as NQO1 in open-access papers (continued):
Sharing a sentence is not in itself a finding about the gene and the disease.
tumor (continued). "Through upregulation of the cell cycle pathway and overexpression of NQO1 and ODC1, they exhibit an aggressive and chemoresistant tumor phenotype as well as a poorly differentiated histology." (PMID 32656360, 2020). "In NQO1+ NSCLC luciferase murine models, β-lap and IR combination therapy reduces tumor volume and increases survival up to 70% in comparison with either agents alone." (PMID 32974194, 2020). "We found that the protein and the mRNA level of Nqo1 and Gstm1 (NRF2 target genes) were drastically elevated in the tumor tissues of the Atg7ΔHep mice." (PMID 32382012, 2020). "Among the genes related to prognosis, the expression levels of CCNB1, NQO1, NUF2, and CHEK1 were high in tumor tissues (p < 0.05)." (PMID 33424998, 2020). "We further examined the antitumor efficacy of β-lap in three subcutaneous syngeneic tumor models: MC38, TC-1, and B16 each with different NQO1 levels." (PMID 31324798, 2019). "Co-culture of bone marrow-derived dendritic cells (BMDCs) and β-lap-treated tumor cells (MC38 and NQO1 overexpressing B16 cells) in vitro significantly increased the production of IFNβ protein." (PMID 31324798, 2019). "Western blotting and IHC revealed increased levels of NQO1 and decreased levels of GSTZ1 in most tumors, compared to tumor-adjacent normal tissues." (PMID 31666108, 2019). "Correlation of Nrf2 downstream transcripts expression with tumor invasiveness and patients survival in NSCLC advanced stage has been also reported for Ho-1 and Nqo1." (PMID 27847554, 2016). "To validate specific upregulation of HIF-1α in NQO1-expressing tumours, we analysed HIF-1α protein levels in tumour tissues." (PMID 27966538, 2016). "Here, an AIE fluorophore is decorated with both a tumor and organelle targeting triphenylphosphonium moiety and a quinone based trigger, allowing the selective activation of the AIE self-assembly by the NQO1 enzyme." (PMID 30034745, 2016). "Collectively, these observations strongly argue for the functional contribution of NQO1 in stabilizing HIF-1α which, in turn, enhances tumour growth in vivo." (PMID 27966538, 2016). "We assessed the levels of NQO1 and HIF-1α in these tumours and found that NQO1 knockdown tumours showed significantly reduced HIF-1α expression, which was associated with decreased proliferation (Ki67) and elevated apoptosis (cleaved caspase 3, CC3)." (PMID 27966538, 2016). "This pattern of enrichment in AC and SCC was also seen with the other NRF2 target genes, GCLC, GCLM and NQO1, although HMOX1 was downregulated in both tumour types." (PMID 27824809, 2016). "Using this approach, 7 genes were identified as undergoing tumor-specific aberrant promoter methylation in HCC, including IFITM1, SMAD6, TBX15, CHST4, and LRRC4 with hyper-methylated promoters and CCL20 and NQO1 with hypo-methylated promoters." (PMID 26300991, 2015). "The NAD(P)H:Quinone Oxidoreductase 1 (NQO1) bioactivatable drug, ß-lapachone (ARQ761 in clinical form), can provide tumor-selective and enhanced synergy with BER inhibition." (PMID 26602448, 2015). "Novel NAD(P)H:quinone oxidoreductase 1 (NQO1, EC1.6.99.2) bioactivatable drugs represent a promising new tool for the novel tumor-selective treatment of PDAs." (PMID 26602448, 2015). "Both positive rate and strongly positive rate of NQO1 protein expression were significantly higher in NSCLC (59.3% and 28.0%) than that in adjacent non tumor (8.0% and 1.3%) and normal lung tissues (0%)." (PMID 25880877, 2015). "More importantly, the positive rate of NQO1 protein in DCIS was also significantly higher (51.1%, 23/45) than hyperplasia (36.7%, 8/22) and adjacent non-tumor tissues (30.8%, 16/52)." (PMID 24499631, 2014).
tumor (continued). "This property confers a high tumor-selectivity and low normal tissue toxicity on TSA and other similar agents such as β-lapachone, which target NQO1 against tumor tissues while sparing normal tissues." (PMID 24244442, 2013). "Damage response protein CHK1 changed from almost no detectable staining in the primary biopsy to 50%, nuclear staining of NQO1 increased from 20 to 70% and TYMS staining increased from below 1% to 25% of tumour cells." (PMID 22905093, 2012). "DIC pretreatment, despite antagonizing the tumor suppression effect of TSA, significantly increased the exposure levels of TSA including that in tumor tissues, by a mechanism of inhibiting TSA metabolism via NQO1/UGTs." (PMID 22848731, 2012). "Overexpression was verified for Thymidylate Synthase, VG5Q, Chk1, NQO1 and RAD21, where tumour cells were positive in most cases." (PMID 19662092, 2009). "In a panel of human tumour cell lines, EO9 is selectively toxic towards NQO1 rich cell lines under aerobic conditions and potency can be enhanced by reducing extracellular pH." (PMID 11710826, 2001). "Changes in NQO1 expression therefore correlated with the level of PDX growth inhibition, irrespective of drug target, and likely reflected a general reduction in NRF2 activity in the growth‐inhibited tumor cells." (PMID 40600748, 2025). "Based on this, we speculate that NQO1 may interact with multiple key glycolytic enzymes, such as lactate dehydrogenase A (LDHA), in CRC, potentially regulating lactate production and tumor metabolism." (PMID 39939940, 2025). "Moreover, IHC analysis of subcutaneous xenograft tumor tissues revealed that the expression of PP1A was positively correlated with that of GPX4 and NQO1, which are crucial for ferroptosis." (PMID 40344394, 2025). "In the primary tumor, both P40 and P63 showed a similar expression pattern as Ki67 and NQO1, and were essentially absent in the centrally located squamous portions." (PMID 40600748, 2025). "We combined the mean fluorescence intensity (MFI) values from the local scan areas with clinical data to evaluate whether the expression levels of NRF2, NQO1, and SLC7A11 varied significantly across different grades and tumor-node-metastasis (TNM) stages." (PMID 40007539, 2025). "Similar results achieved by TRK and PI3K inhibitors are unsurprising, as multiple signaling pathways may alter tumor cell metabolism and NRF2‐mediated NQO1 activation through different mechanisms." (PMID 40600748, 2025). "Higher magnification images clearly showed that, while NQO1 expression in both tumor and stroma areas was very low in the WT tumor tissues, a high level of NQO1 expression was detected in the tumor area but not in the stroma area of the KEAP1-KO tumor tissues." (PMID 41035689, 2025). "We observed that VPA effectively blocked the transcription of FTL, FTH1 and NQO1 in tumor tissues, with or without Erastin treatment, and DFS treatment didn't affect the function of VPA." (PMID 40963919, 2025). "A greater level of this quinone bioactivation due to elevated NQO1 content has been recognized as a tumor-specific therapeutic strategy, which, however, has not been clinically exploited." (PMID 39120303, 2024). "Using confocal fluorescence microscopy, the authors imaged NQO1-positive HT29 cells from negative H596 tumor cells successfully with a positive-to-negative ratio of 500:1." (PMID 39120303, 2024). "Furthermore, our data showed that the key genes, TRIB3 and NQO1, were not only correlated with the survival outcome and clinical stage of HCC but were also highly expressed within a subpopulation of tumor cells characterized by enhanced stemness." (PMID 39044829, 2024). "Here, we compared the tumor spheroid-forming ability of NSCLC cells with or without the expression of NQO1." (PMID 36980879, 2023). "A549 cells expressing NQO1 have an approximately 12-fold increase in tumor-initiating cells in comparison with A549 cells lacking NQO1 expression (A549-shNQO1)." (PMID 36980879, 2023).
tumor (continued). "NQO1 (NAD(P)H quinone dehydrogenase 1) is not beneficial to ferroptosis and is closely related to the tumor immune microenvironment." (PMID 35232428, 2022). "Following the intravenous administration of the tested probe, intense fluorescence was observed only for the NQO1-positive A549 tumor, whereas there was no discernible signal in the NQO1-negative MDA-MB-231 tumor." (PMID 35681666, 2022). "In tumor cells, the expression level of NQO1 was very high, while the normal lines did not express the protein." (PMID 35681666, 2022). "In addition, compared to the lanthanide-mediated suppression of NQO1 alone, the inhibition of both NQO1 and NQO2 by HOXA11-AS knockdown markedly enhanced the suppression of tumor growth and metastasis, with a particularly strong effect in the latter." (PMID 36142607, 2022). "Therefore, multiplex immunofluorescence was performed to examine the co-localization of NQO1, NRF1 and NRF2 within the tumor and TME." (PMID 36359002, 2022). "The antioxidant genes NQO1, GSTP1, PRDX1 and NQO1 were upregulated specifically in detached cells, indicating that antioxidant mechanisms were not fully capable of protecting tumor cells against the PDT-inflicted oxidative injuries." (PMID 34371724, 2021). "Consistently, markedly higher NQO1:CAT ratios were observed in these tumor samples than in normal samples (p = 1.5×10-9)." (PMID 34676172, 2021). "We lastly examined the NQO1 expression in both HCC and the paired non-tumor tissues." (PMID 33648552, 2021). "Both in vitro and in vivo studies demonstrated that ZIF67/Ola/Lapa presented remarkable capability in the inhibition of NQO1 overexpressed MDA-MB-231 cells and tumor progression without toxicity to normal tissues owing to the low NQO1 expression." (PMID 34481495, 2021). "Therefore, the synergy of PARP inhibitor (PARPi) and Lapa is a promising strategy to extend NQO1-mediated H2O2 generation, inhibit PARP-driven DNA repair and enhance DNA damages in a tumor-selective manner." (PMID 34481495, 2021). "We observed the upregulated expression of NQO1 in tumor tissues when comparing with the paired non-tumor samples." (PMID 33648552, 2021). "Previous studies have indicated that tumors elevate NQO1 to enhance the cell survival and reduction of NQO1 potentially ameliorates the negative effects of tumor-NQO1 overexpression on patient outcome." (PMID 33087132, 2020). "It was showed that NQO1 overexpression may be identified as an independent prognostic biomarker in PDAC, and connected with the tumor-node-metastasis (TNM) stage." (PMID 32537471, 2020). "Hence, these findings suggested that NQO1 and GSTP1 were upregulated in the tumor tissues of GBM patients, and their expression was correlated." (PMID 33087132, 2020). "Moreover, high levels of activation of the Nrf2 pathway (evaluated as high NQO1 expression) in human HCC correlated with elevated α-fetoprotein, large tumor size, worse prognosis, and higher incidence of recurrence." (PMID 33053665, 2020). "Furthermore, the effect of NQO1 and SIRT6 on tumor growth was determined in cell model and orthotopic tumor implantation model." (PMID 31842909, 2019). "The results showed that neither naive CD8+ T from spleen nor tumor-infiltrating CD8+ T cell expressed NQO1." (PMID 31324798, 2019). "Furthermore, IHC analysis showed that NQO1 knock-out was related with reduced level of SIRT6, XIAP and increased level of cleaved PARP in tumor tissues." (PMID 31842909, 2019). "NAD(P)H:quinone oxidoreductase 1 (NQO1) is highly enriched in multiple tumor types and has emerged as a promising target for direct tumor-killing." (PMID 31324798, 2019). "In the mitomycin C-resistant tumour cell lines, HCT 116-R30A solely the mRNA of NQO1*3 could be detected while in the mitomycin C sensitive HCT 116 cell line mRNAs of NQO1*1 and NQO1*3 were detectable." (PMID 28236663, 2017). "In this current study, expression of NQO1 was significantly higher in tumour as compared to matched nontumour specimens." (PMID 28748640, 2017).
tumor (continued). "Similarly, the strongly positive rate of NQO1 expression was 28.0% (42/150) in NSCLC, which was also significantly higher than that in adjacent non-tumor (1.3%, 2/150) (P < 0.01)." (PMID 25880877, 2015). "Overall, the findings of this study indicate that miR-372 is able to evoke migration and increase ROS via targeting of p62, which may decreases NQO1 expression then, and the circulatory miR-372 could be HNSCC tumor marker." (PMID 25714028, 2015). "We also observed similar trends in NQO1 induction in tumor cells treated with another AIM, bardoxolone methyl (data not shown)." (PMID 26301506, 2015). "By combining GLS1 inhibition (e.g., CB-839) and NQO1-bioactivatable drugs (e.g., β-lap, ARQ761), we exploit the reliance of PDA on glutamine for redox balance, as well as the tumor-selective overexpression of NQO1 through the use of a unique agent that is bioactivated to induce cell death." (PMID 26462257, 2015). "In this trial, bardoxolone methyl increased the expression of NQO1 in peripheral blood mononuclear cells and decreased NF-κB and cyclin D1 levels in tumor biopsies." (PMID 26301506, 2015). "On the other hand, activation of NQO1 can promote the death of some types of non-neural tumor cells." (PMID 23874855, 2013). "Using a chromosome 16q-specific cDNA array to identify tumor suppressor genes we have found five candidates, of which the two most interesting, NQO1 and ATBF1, were excluded as classical candidate genes." (PMID 18416817, 2008). "Although we have previously shown that induction of NQO1 in human and murine tumours and in human and murine bone marrow cells is similar, induction of NQO1 in other human tissues has not been extensively studied." (PMID 15467770, 2004). "Notably, all grade 1 tumours were NQO1‐negative, while the majority of NQO1‐positive tumours were high grade (50% grade 3 and 77.8% grade 4) (p < .0001)." (PMID 39707614, 2025). "The effect of NQO1 on the tumor immune microenvironment was not thoroughly studied." (PMID 37583897, 2023). "Recent studies suggested KP372-1 as a promising and potent NQO1-dependent anti-tumor agent that induced dramatic ROS generation and DNA damage, leading to PARP1 hyperactivation and a decrease in NAD+/NADH redox state, which suppressed tumor cell growth in vitro and in vivo." (PMID 36203459, 2022). "Moreover, in vivo studies in a mouse model showed that NQO1 was present only in the tumor tissue and not in the other ones." (PMID 35681666, 2022). "Moreover, up-regulated of TRIM15 increased Nrf2 and the target gene NQO1 expression in subcutaneous tumor tissues, an observation not seen with co-expression of TRIM15 with Nrf2shRNA." (PMID 35534896, 2022). "However, the combination of THC and NQO1 inhibitor exerted a superior effect on tumor growth than THC monotherapy in ESCC-PDX, suggesting that NQO1 expression might be a critical biomarker of THC response in ESCC patients." (PMID 33903283, 2021). "However, we observed the downregulation of NQO1 in tumor tissue after SDT, which apparently did not match with the upregulation of NFE2L2." (PMID 34681196, 2021). "Indeed, we observed a dose-dependent secretion of HMGB1 in NQO1+ tumor cells but not in NQO1− cells." (PMID 31324798, 2019). "In our study, in both types of HCCs, NASH-related and HCV+, two downstream proteins of Nrf2, namely, NQO1 and SOD2, which participate in ROS elimination, were found induced, indicating that Nrf2 plays an important role in adaptation to oxidative stress in the tumor." (PMID 28218651, 2017).
tumor (continued). "DIC treatment alone also slightly inhibited the tumor growth characterized with the tumor volume of 439±99 mm3; to the contrary, DIC pretreatment significantly antagonized the tumor suppression effect of TSA, suggesting that the antitumor effect of TSA in vivo was also NQO1 dependent." (PMID 22848731, 2012). "Furthermore, these agents are not subject to metabolism by NQO1/DT-diaphorase enzymes nor to efflux by P-glycoprotein, and tumor cells in culture that have acquired resistance to 17-AAG remain susceptible to these newer agents." (PMID 20628489, 2010). "However, the one electron reductases implicated in MMC activation are unlikely to be responsible for NQO1 independent activation of MMC in tumours in an aerobic environment." (PMID 17031400, 2006). "However, given NQO1’s ability to alleviate oxidative stress damage, regulate cell cycle progression, and counteract cell transformation and tumor formation, the increased expression of NQO1 may not be a detrimental factor promoting NPC aging." (PMID 39328407, 2024). "Furthermore, ferroptosis-related genes with copy number amplification (including FADS2, NQO1, ABCC1, ACSF2, HMOX1, FANCD2 and SQLE) demonstrated higher expression in tumour tissues, and those with copy number deletion (including CRYAB, ACSL3, ZEB1) demonstrated lower expression in tumour tissues." (PMID 35145965, 2022). "The finding that treatment of the mice with the NQO1 inhibitor, DIC, prior to MMC partially reversed the enhanced antitumour activity in DMF fed mice strongly supports the hypothesis that the increased antitumour activity was due to the increased NQO1 activity in the tumour." (PMID 15467770, 2004). "While tumor cells do not have high expression of NFE2L2 relative to myeloid cells, elevated expression occurs downstream of the Nrf2 pathway (NQO1, GPX2), which regulates oxidative damage repair." (PMID 35995947, 2022). "Conversely, the tumor suppressor and negative modulator of oxidative stress, NAD(P)H dehydrogenase (NQO1), is lost in cSCC." (PMID 35666359, 2022). "To confirm this observation, we conducted RT-qPCR analysis using 40 tumor samples from HCC patients to detect GSTZ1 and NQO1 mRNA expression, and we observed a negative correlation between GSTZ1 and NQO1 expression (r = − 0.37, p = 0.0197)." (PMID 31666108, 2019). "We proved that tumor-infiltrated CD8+ T cell lack NQO1 and that β-lap has no cytotoxic effect on native and activated CD8+ T cell even at the tumor-lethal dose." (PMID 31324798, 2019). "The positive rate of the NQO1 protein expression was 59.3% (89/150) in NSCLC tissues, which was significantly higher than that in adjacent non-tumor (8.0%, 12/150), and the expression were all negative in normal lung tissues (P < 0.01)." (PMID 25880877, 2015). "Spearman’s correlation analysis for the mRNA expression of NRF2 pathway genes in normal and tumor tissues from our institutional cohort also revealed high concordance in expression between DPP3 and NRF2 pathway genes, including NFE2L2, KEAP1, and NQO1 in tumors, but not in normal tissues." (PMID 37531267, 2023). "Recent NSCLC studies demonstrate NQO1 and NRF2 negativity in normal tissue and NQO1 and NRF2 upregulation in tumor tissue, proposing single-negative NQO1 expression and dual-negative expression of NRF2 and NQO1 are predictive of improved outcomes in NSCLC patients." (PMID 36359002, 2022). "Individual protein analysis for NQO1, NRF1 and NRF2 and triple-negative phenotyping (NQO1−NRF1−NRF2−) failed to generate clinically-relevant high and low cut-offs, showing no significance in tumor cells." (PMID 36359002, 2022). "Supporting the role of GARP in mediating the macrophage–tumor interaction, M1-like macrophages derived from GARP knockout mice (GARP KO M1) did not demonstrate the induction of methylation in the Nqo-1 gene by mouse KPC PDA cells comparing to wild-type M1-like macrophages (WT M1)." (PMID 34711804, 2021).